SLC2A1 (solute carrier family 2 member 1)
Diseases named in the same sentence as SLC2A1 in open-access papers (continued):
Sharing a sentence is not in itself a finding about the gene and the disease.
developmental delay (38 papers, 2010 to 2026). "Our study enriches the SLC2A1 gene mutation spectrum and emphasizes the importance of molecular genetic study in patients with neuropsychomotor developmental delay." (PMID 39629096, 2024). "Our study enriches the SLC2A1 gene mutation spectrum and emphasizes the importance of molecular genetic studies for screening patients with neuropsychomotor developmental delay." (PMID 39629096, 2024). "Sentence take-home message (synopsis) of the article: The study enriches the SLC2A1 gene mutation spectrum and emphasizes the importance of molecular genetic studies for screening patients with neuropsychomotor developmental delay." (PMID 39629096, 2024). "Therefore, the SLC2A1 gene can induce skeletal regeneration; at the same time, GLUT-1 deficiency causes developmental delay." (PMID 37239409, 2023). "Mutations in SLC2A1, which encodes the glucose transporter GLUT1, most commonly cause de vivo or GLUT1 deficiency syndrome (GLUT1 DS), characterized by infantile seizures, acquired microcephaly, developmental delay, and motor incoordination consisting of ataxia and dystonia (OMIM #606777)." (PMID 33126486, 2020). "In infants with seizures, developmental delays, or motor dysfunction, CSF analysis and targeted SLC2A1 testing are essential." (PMID 41624815, 2026). "Given the presence of early-onset seizures, developmental delay, microcephaly, and progressive spasticity, genetic testing was performed, revealing a pathogenic variant in SLC2A1, confirming a diagnosis of GLUT1 deficiency syndrome (GLUT1-DS)." (PMID 40243517, 2025). "SLC2A1 (solute carrier family two member 1): Glucose transporter type 1 deficiency syndrome (GLUT1-DS) is characterized by seizures, developmental delay, and movement disorders." (PMID 37927689, 2023). "For children with unexplained epileptic seizures, developmental delay, and complex movement disorders, detection of low CSF glucose or SLC2A1 gene mutations is helpful for the diagnosis of GLUT1-DS." (PMID 34880899, 2021). "Heterozygous Slc2a1 knockout mice present features of the human GLUT1 deficiency syndrome, a rare metabolic disease characterized by developmental delay and infantile seizures caused by a defective glucose transport across the blood–brain barrier but no metabolic abnormalities." (PMID 32591906, 2020). "The most striking example of this is seen in GLUT1 deficiency, where mutations in the SLC2A1 gene, which encodes a glucose transporter in the blood brain barrier (GLUT1), lead to low glucose in the cerebrospinal fluid, resulting in seizures and developmental delay." (PMID 33619078, 2021). "In fact, GLUT1-DS is a rare disease caused by mutations in the SLC2A1 gene that encodes the glucose carrier protein type 1 (GLUT1), the main carrier of glucose across the blood-brain barrier, which is characterized by early-onset seizures, developmental delay, and a complex movement disorder." (PMID 31349661, 2019). "Because of a mutation in the SLC2A1 gene, GLUT 1 is lacking, causing a severe developmental delay, intellectual disability, and other neurological symptoms." (PMID 30127309, 2018).
squamous cell carcinoma (38 papers, 2009 to 2026). A carcinoma arising from squamous epithelial cells. "In summary, the SLC2A1 -2841A>T polymorphism was associated with FDG-uptake in combination with the APEX1 TT genotype in patients with squamous cell carcinoma." (PMID 20540786, 2010). "We analyzed subgroups according to the combinations of SLC2A1, VEGFA, APEX1, and HIF1A polymorphisms in patients with squamous cell carcinomas." (PMID 20540786, 2010). "In patients with squamous cell carcinomas, the mean SUVmax of the SLC2A1 TT and AA + AT genotypes (recessive model) were 10.64 ± 2.26 and 9.07 ± 2.79, respectively, with no statistical significance (P = 0.130)." (PMID 20540786, 2010). "The expression of SLC2A1 in squamous cell carcinomas was higher than adenocarcinomas." (PMID 20540786, 2010). "In our study, the significance of SLC2A1 gene polymorphisms on FDG-uptake was consistently observed for squamous cell carcinomas, but not for adenocarcinomas." (PMID 20540786, 2010). "We selected two proteins consistently overexpressed in squamous cell carcinoma in all studies, MCT1 (SLC16A1) and GLUT1 (SLC2A1), for further investigation." (PMID 26539827, 2015).
type 2 diabetes (36 papers, 2011 to 2025). "In the study of non-tumor diseases, evidence suggests that high expression of SLC2A1 is associated with type 2 diabetes and its complications, as well as chronic inflammation." (PMID 38517368, 2024). "An association study was conducted to investigate the relation between 14 variants of glucose transporter 1 gene (SLC2A1) and the risk of type 2 diabetes (T2DM) leading to nephropathy." (PMID 30353771, 2018). "Nevertheless, according to a study of two populations in the Pacific, the variant rs841853 of SLC2A1 was not predisposing to diabetes type 2." (PMID 30353771, 2018). "Treatment with roxadustat led to induction of HIF target gene mRNAs for GLUT1 (also known as SLC2A1), HK2, MCT4 (also known as SLC16A4) and HIF-P4H-2 (also known as PHD2 or EGLN1) in myotubes from donors with NGT, with a blunted response in myotubes from donors with type 2 diabetes." (PMID 38814443, 2024). "SLC2A1 (GLUT1), a high-affinity glucose transporter expressed ubiquitously, has been shown to be a susceptibility factor of NAFLD20; several single nucleotide polymorphisms (SNPs) are also closely related to NAFLD but not to type 2 diabetes." (PMID 31956272, 2020). "SLC2A1 may not be involved in the pathogenesis of type 1 diabetes but its involvement in type 2 diabetes is plausible according to functional criteria." (PMID 30353771, 2018).
lymph node metastasis (35 papers, 2010 to 2025). "Additionally, SLC2A1 expression correlated with tumor size (T) and lymph node metastasis (N), with higher levels associated with advanced T and N stages." (PMID 40276602, 2025). "High SLC2A1 levels in patients with CRC have been correlated with an increased incidence of lymph node metastasis and mortality." (PMID 39858431, 2024).
Ataxia (33 papers, 2010 to 2025). Ataxia refers to impaired coordination of voluntary muscle movement. "The patient with a variant in SLC2A1 showed significant improvement of their ataxia after ketogenic diet recommendation and was able to walk alone at 5 years of age." (PMID 35719373, 2022). "In this study, we report a novel heterozygous frameshift variant (c.855_856insTT; p.Gly286Leufs*55) in the SLC2A1 gene in a preschool Brazilian child with atypical phenotype of GLUT1 deficiency syndrome, characterized by ataxia and mild speech delay." (PMID 39629096, 2024). "Based on a list of keywords related to ataxia and seizure, we narrowed the number down to 14 candidate genes, and one of them, Slc2a1 (glucose transporter 1; Glut1), was a strong candidate." (PMID 31399478, 2019). "EA is a clinically heterogeneous disorder characterized by recurrent spells of ataxia lasting minutes to hours which has been associated over time to a number of genes besides CACNA1A and KCNA1 (CACNB4, SLC1A3, FGF14, SLC2A1, ATP1A3, PRRT2) accounting for the majority of cases." (PMID 32823520, 2020).
renal cell carcinoma (31 papers, 2006 to 2024). "For example, in renal cell carcinoma, miR-1291 induces cell proliferation, migration and invasion by targeting solute career family 2 member 1 (SLC2A1), which encodes for GLUT1." (PMID 29374351, 2018).
Dystonia (30 papers, 2013 to 2025). An abnormally increased muscular tone that causes fixed abnormal postures. "These disorders are frequently related to heterozygous variants of SLC2A1 (PxMD-SLC2A1, dystonia 9, DYT9, OMIM#601042)." (PMID 40724495, 2025). "Variants in movement disorder genes frequently comprising dystonia as a phenotype included recurrent variants in ADCY5, C19orf12, and SLC2A1." (PMID 40533913, 2025). "We also noted that three of the genes identified as chordoma dependency genes (THAP1, SLC2A1, and PRKRA) are causative for dystonia, a neurological condition characterized by involuntary muscle contractions." (PMID 37024492, 2023). "1, ADCY5), Glut1 syndrome (SLC2A1), and myoclonus‐dystonia (SGCE)." (PMID 36054588, 2022). "Furthermore, the features that were common among previously reported cases but were absent in the PEDIATAX cohort included dystonia with ATM; and spasticity, dystonia, abnormal reflexes, and intellectual disability with SLC2A1." (PMID 40326640, 2025).
Cognitive impairment (29 papers, 2015 to 2026). Abnormal cognition is characterized by deficits in thinking, reasoning, or remembering. "Mutations in Slc2a1 cause GLUT1 deficiency syndrome and cognitive impairment." (PMID 40114059, 2025). "Moreover, GLUT1 deficiency leads to early BBB breakdown in Slc2a1+/- mice, and decreased GLUT1 protein expression is found in the brain microvessels of patients with AD and cognitive impairment." (PMID 32257549, 2020). "In addition to AD, GLUT1 deficiency syndrome, also known as De Vivo disease, is a rare genetic metabolic disorder caused by SLC2A1 gene, is inherited as an autosomal dominant trait, and is associated with mild to severe cognitive impairment." (PMID 35517047, 2022).
psoriasis (29 papers, 2017 to 2024). An autoimmune condition characterized by red, well-delineated plaques with silvery scales that are usually on the extensor surfaces and scalp. "According to recent reports, SLC2A1 plays role in UV-irradiated mouse skin, during wound healing responses, and in psoriasis." (PMID 37205116, 2023). "In comparison with normal samples, the glycolysis score was significantly higher in psoriasis samples in KRT5+ KRT14+ KC, KRT1+KRT10+ KC, and LDHA+SLC2A1+ KC (all P<0.001)." (PMID 37205116, 2023).
breast tumor (27 papers, 2010 to 2025). "Meanwhile, we analyzed the gene expression profiling data of SLC2A1 from GEPIA, and found SLC2A1 was significantly up-regulated in breast tumor compared with normal tissue." (PMID 31138773, 2019). "To extend these observations to human breast tumors, we evaluated SLC2A1 expression in the normal breast, DCIS, and IDC samples from a publicly available gene expression dataset." (PMID 27998284, 2016). "We found that the mRNA expression levels of SLC2A1 were significantly higher in the breast tumor." (PMID 37108300, 2023). "Finally, we utilized global gene expression profiling data of primary human breast tumors to determine the relationship between SLC2A1 and stage of tumorigenesis." (PMID 27998284, 2016). "Among these genes, the basal expression level of SLC2A1 is the highest not only in MDA-MB-231 cells, but also in breast tumor." (PMID 31138773, 2019). "Specifically, SLC2A1, SLC2A6, SLC2A10, and SLC2A13 were significantly overexpressed, whereas SLC2A3, SLC2A4, SLC2A9, SLC2A11, and SLC2A12 had downregulated expressions in breast tumors compared with those in normal breast epithelium." (PMID 37108300, 2023). "In both cohorts examined, SLC2A1 mRNA expression is significantly elevated in basal-like subtype (corresponding to the most common subtype of TNBC11) compared to estrogen receptor positive and HER2-amplified breast tumors (TCGA: p = 3.33e−11; METABRIC: p = 2.53e−8)." (PMID 32826891, 2020).
laryngeal carcinoma (27 papers, 2014 to 2026). Carcinoma that arises from the laryngeal epithelium. "PXN, ITGB1, ISG15, SLC2A1 and ICAM1 are regarded as potential therapeutic targets for HPV-positive laryngeal cancer." (PMID 40821990, 2025). "This further emphasizes that SLC2A1 has a great potential to be a prognostic marker and a therapeutic target for HPV-positive laryngeal cancer." (PMID 40821990, 2025). "ISG15, ITGB1, PXN, SLC2A1 and ICAM1 are expected to become potential therapeutic targets for HPV-positive laryngeal cancer." (PMID 40821990, 2025). "Key genes like CDC42, PXN, ITGB1, PGK1, SLC2A1, ISG15 and ICAM1, affected by HPV, display distinct functional alterations and complex correlations in laryngeal cancer progression." (PMID 40821990, 2025). "In conclusion, our findings suggest that both the SLC2A1 and SLC2A3 genes, as well as the related GLUT1 and GLUT3 proteins, can affect the behavior of laryngeal cancer." (PMID 25412955, 2015). "A positive expression of SLC2A1 and SLC2A3 transcripts was confirmed in 83.9 % (89/106) and 82.1 % (87/106) samples of laryngeal cancer, respectively." (PMID 25412955, 2015). "A significant difference was noted in the levels of GLUT1 and GLUT3 mRNA in laryngeal cancer tissue compared to adjacent normal laryngeal tissue (p < 0.001 and p < 0.001, for the SLC2A1 and SLC2A3 genes, respectively)." (PMID 25412955, 2015). "Positive expression of SLC2A1, SLC2A3, and HIF-1α genes was noted in 83.9, 82.1, and 71.7 % of SCC specimens and in 34.4, 59.4, and 62.5 % of laryngeal cancer samples." (PMID 25412955, 2015). "Gene copy number analysis revealed that SLC2A1 gene amplification was observed in 2 % (2/106) of laryngeal cancer cases, but in none of the normal tissue samples." (PMID 25412955, 2015). "Since copies of the studied genes were found in only 2 % cases of laryngeal carcinoma, it can be concluded that SLC2A1 and SLC2A3 amplification does not affect the expression of GLUT1 and GLUT3 in this type of neoplasm." (PMID 25412955, 2015).
microcephaly (26 papers, 2010 to 2025). A congenital or acquired developmental disorder in which the circumference of the head is smaller than normal for the person's age and sex. "Consistently, knockout of SLC2A1, a down-regulated gene, has been verified to be associated with neurodegeneration, behavioral deficits and microcephaly, i.e. abnormally small head in mice." (PMID 32131728, 2020). "Interestingly, we found several differentially expressed genes following infection with ZIKV Uganda, including COL4A1, MIR17HG, TUBA1A, SLC2A1 and STAMBP, which are associated with microcephaly according to the comparative toxicogenomics database." (PMID 33121145, 2020).
liver cancer (25 papers, 2007 to 2025). An epithelial or non-epithelial malignant neoplasm that arises from the liver. "Glucose transporter 1 (GLUT1) encoded by SLC2A1 is the primary regulator of glucose uptake and contributes to the metastasis and chemoresistance of liver cancer." (PMID 35560794, 2022).
leukemia (24 papers, 2012 to 2025). A malignant (clonal) hematologic disorder, involving hematopoietic stem cells and characterized by the presence of primitive or atypical myeloid or lymphoid cells in the bone marrow and the blood. "We noted a consistent upregulation of glucose importers SLC2A1 and SLC2A3 in leukemic cells, but also various other glycolysis-related genes were upregulated in leukemia although variation between different cell lines was noted as well." (PMID 31890203, 2019). "Liu and collaborators recently showed a lower expression of the SLC2A3 gene (GLUT3), but not of the SLC2A1 gene (GLUT1), in leukemia blasts compared with normal hematopoietic cells." (PMID 33804775, 2021).
osteosarcoma (24 papers, 2012 to 2025). A usually aggressive malignant bone-forming mesenchymal neoplasm, predominantly affecting adolescents and young adults. "In osteosarcoma, we constructed a prognostic model for SLC2A1 and FBP1, and the prognosis of the patient can be predicted based on the risk score of expression." (PMID 36316355, 2022). "This study used multivariate COX regression analysis to select the hypoxia genes SLC2A1 and FBP1 in patients with osteosarcoma, and used the expression of these two genes to divide the patients with osteosarcoma into high-risk and low-risk groups." (PMID 36316355, 2022). "We screened out the promising hypoxia genes SLC2A1 and FBP1 in osteosarcoma, and the patient risk score based on gene expression is related to the degree of tumor infiltration of multiple immune cells." (PMID 36316355, 2022). "The results of univariate Cox regression analysis showed SLC2A1, ENO1, FBP1 and PGM1, while multivariate COX regression analysis showed that SLC2A1 and FBP1 could indicate the prognostic risk of patients in osteosarcoma." (PMID 36316355, 2022). "Therefore, in this study, we screened out the hypoxia genes SLC2A1 and FBP1 in patients with osteosarcoma through multivariate COX regression analysis, and used the expression of these two genes to divide patients with osteosarcoma into high-risk and low-risk groups." (PMID 36316355, 2022). "This study constructed a prognostic model based on hypoxia-related genes SLC2A1 and FBP1 in patients with osteosarcoma, and explored their correlation with immune cells, inflammatory markers and ferroptosis-related genes." (PMID 36316355, 2022). "This indicates that SLC2A1 and FBP1 are promising targets for osteosarcoma research." (PMID 36316355, 2022). "Therefore, in this study, we first screened two prognostic-related hypoxia genes, Solute Carrier Family 2 Member 1 (SLC2A1) and Fructose-Bisphosphatase 1 (FBP1), in osteosarcoma." (PMID 36316355, 2022). "Therefore, in this study, we constructed a prognostic model based on hypoxia-related genes SLC2A1 and FBP1 in patients with osteosarcoma, and explored its correlation with immune cells, inflammatory markers and ferroptosis-related genes." (PMID 36316355, 2022). "This suggests that SLC2A1 and FBP1 are promising research targets in osteosarcoma." (PMID 36316355, 2022).
lymphoma (23 papers, 2012 to 2025). A malignant (clonal) proliferation of B- lymphocytes or T- lymphocytes which involves the lymph nodes, bone marrow and/or extranodal sites. "The SLC2A1 HaeIII and HpyCH4V SNPs were also associated with Ann Arbor stage, a well-established measure of lymphoma distribution." (PMID 34708297, 2022). "Altered expressions of SLC2A family members have been reported in many types of cancer (liver- SLC2A1, SLC2A2, SLC2A5; pancreas- SLC2A1; breast- SLC2A1, SLC2A2, SLC2A4; stomach- SLC2A2, SLC2A4, SLC2A5, SLC2A14; lymphoma- SLC2A5)." (PMID 28978124, 2017).
ischemia (21 papers, 2006 to 2025). A hypoperfusion of the BLOOD through an organ or tissue caused by a PATHOLOGIC CONSTRICTION or obstruction of its BLOOD VESSELS, or an absence of BLOOD CIRCULATION. "Even though SLC2A1 is generally considered to be an insulin-independent glucose transporter, membrane translocation has previously been observed in an insulin-dependent manner during ischemia in cardiomyocytes, similar to the presented culture conditions." (PMID 32656187, 2020).
Intellectual disability (20 papers, 2011 to 2025). "In particular, suspicion for SLC2A1 mutations should be raised when there is a combination of atypical features in absence epilepsy, including early age of onset, intellectual disability, treatment refractoriness, other seizure types, or family history." (PMID 33833732, 2021).